CD4 (CD4 molecule)
Diseases named in the same sentence as CD4 in open-access papers (continued):
Sharing a sentence is not in itself a finding about the gene and the disease.
tumor (continued). "To measure whether enhanced DcR3 expression from HCC cells inhibited CD4+ T-cell differentiation and secretion by binding to ligand LIGHT, we first reviewed the cytokine expression profile and found that LIGHT expression was upregulated in tumours compared with normal tissues." (PMID 31409774, 2019). "Further analysis of the tumor infiltrate also showed that the combination of p-Tvax and OX40 agonists produced other effects that may favor tumor clearance such as the reduced expression of the T cell exhaustion marker PD-1 in CD4+ T cells and the decrease in number of Tregs." (PMID 31428586, 2019). "However, a high CD4+/CD8+ ratio was not related to tumor cell dissemination in our study." (PMID 30717704, 2019). "Therefore, it would be important to investigate whether MHC class I-restricted CD4+ T cells are sufficient to support anti-tumor immunity, or whether physiological MHC class II-restricted CD4+ T cells would play distinct roles in the presence or absence of MHC class II+ antigen-presenting cells." (PMID 30626427, 2019). "The increase in tumor-infiltrating CD4+ T cells following treatment with LTX-315 alone and the combination, may indicate reshaping of the tumor microenvironment from immunosuppressive CD4+ Tregs to a different CD4+ T cell phenotype important for antitumor immunity." (PMID 30670061, 2019). "The higher frequency of memory CD4+ and CD8+ T cells in the spleens of the combination-treated mice indicated that the IRE induced an immunogenic cell death, and the dying tumor cells may have functioned as tumor vaccines to generate a long-term anti-tumor immunity." (PMID 30796212, 2019). "Thus, although SM16 administration resulted in significantly inhibited tumor growth and concomitant increase in the CD4+CD25−FoxP3+ Treg-like subpopulation, it did not significantly increase the CD4+CD25+FoxP3+ Treg subpopulation in the spleen, lymph nodes or tumor microenvironment of TBM." (PMID 31288845, 2019). "Furthermore, eliminated CD4+T cells and/or CD8+T cells from wild-type tumor-bearing mice could not affect the tumor growth of mice, indicating that Th9 cells could directly promote the growth of tumor cells by secreting IL-9." (PMID 31414895, 2019). "However, it is not known whether the anti-CD4 mAb treatment activates a particular or a broad spectrum of tumor-reactive CD8+ T cell clones." (PMID 30733724, 2018). "Interestingly, except that TIGIT was reported to be expressed on NK and T cells, the expression of PVR was also observed on CD4+ T cells, CD8+ T cells and NK cells, indicating the function of these cells might be suppressed by TIGIT on tumor cells via interaction with PVR." (PMID 30555485, 2018). "Interestingly, the numbers of CD4+ and CD8+ cells detected in the tumor tissue sections from curcumin and apigenin-treated mice were apparently increased compared to that from control samples, suggesting that both flavonoids stimulated immune cell infiltration into tumor tissues." (PMID 30373602, 2018). "Finally, they have demonstrated, by immune cell depletion, that both CD8+ and CD4+ T cells are required to establish antitumor immunity and they observed an increased number of IFN-γ producing CD8+ T cells and infiltration of cytotoxic CD8+ T cells within the tumor upon vaccination." (PMID 30510968, 2018). "A higher CD8A expression was expected, since increased numbers of CD8+, FoxP3+, and CD4+ TILs in HPV-positive vs. HPV-negative OPSCC have been noted earlier, where in particular a higher number of CD8+TILs is linked to a better clinical outcome, irrespective of the HPV status of the tumor." (PMID 29587383, 2018). "Non-secreted forms of tumor neoAg may only poorly stimulate specific naive CD4+ T cells." (PMID 29844317, 2018). "Interestingly, we could not find an alteration in Foxp3+ CD4+ previously gated on CD4+ CD25+ tumor infiltrating T cells between both mice strains but an enhanced accumulation of CD4+ PD-1+ T cells in the lung tumors of STAT1 KO mice." (PMID 30647851, 2018).
tumor (continued). "Anergy induction and pTreg conversion observed in activated tumor-specific CD4+ T cells could be the consequence of a lack of inflammatory signals in the tumor microenvironment leading to incomplete maturation of the APCs carrying the DBY Ag from the tumor to the TdLN." (PMID 29844317, 2018). "However, it is not known whether the anti-CD4 mAb treatment expands a part of the highly activated tumor-specific CTL clones or mobilizes a wide variety of tumor-reactive CD8+ T cell clones into the antitumor CTL response." (PMID 30733724, 2018). "To determine whether Kindlin-3 expression may reflect the amount of tumor infiltrating leukocytes (TILs) we analyzed the mRNA levels of different immune markers in the same series of tumors and found that triple negative and ERBB2 tumors presented the highest levels of CD45, CD86, CD28 and CD4." (PMID 30477537, 2018). "IL-2/CD40 slowed tumor growth in both age groups (completely in young, partially in elderly) and this may be explained by our observations that IL-2/CD40 induced several common effects on tumor-infiltrating CD11c+ cells, CD8+ T cells, and CD4+ T cells from both age groups." (PMID 30560130, 2018). "Furthermore, IL-37 mediated tumor suppressing ability may be confined to inhibition of tumor proliferation through its action on CD4+ activation without having effects on tumor metastasis." (PMID 29641433, 2018). "Whole-cell vaccination provides multiple known and unknown TAAs to activate CD4+ T helper and CD8+ cytotoxic lymphocytes (CTL) simultaneously via the vast amount of uncharacterized and characterized T cell epitopes, decreasing the chance of tumor immune escape." (PMID 29115974, 2017). "However, the high level of CD39 expression in both, CD4+ and CD8+ T cells, causes inhibition of the adhesion molecule expression necessary for transendothelial migration into the tumor and may explain the lack of infiltrating T-CD8 cells in the tumor nests." (PMID 28264447, 2017). "The over-expression of CD39 but not PD-1 on CD4+ T cells in NILs suggested that CD39 or PD-1 alone might not contribute to tumor-specific immune suppression, and that co-expression of CD39 with PD-1 in TILs indicated a T-cell dysfunction mechanism used by tumor cells to evade host immune response." (PMID 28603527, 2017). "Moreover, the tumor immunity could be transferred into naive recipients with inhibin-α primed CD4+ T cells, B cells, or serum but not with primed CD8+ T cells." (PMID 28428886, 2017). "Moreover, it was found that the levels of CD4+CD25+FOXP3+ Treg cells in the peripheral blood of advanced (stage III-IV) HCC patients were higher than those of early (stage I-II) HCC patients, which implies that the presence of CD4+CD25+ Treg cells was closely related to tumor progression." (PMID 28796055, 2017). "It was reported in mice that tumor-induced B10s could convert resting CD4+ non-Tregs into Tregs." (PMID 28243231, 2017). "Similarly, OVA-specific CD4+ iTSCM cells also survived in the sentinel lymph nodes and suppressed E.G7-OVA cell growth more efficiently than CD4+ TEM and TCM cells, iTCM cells, and CD62L+ cells, although CD4+ iTSCM cells showed weaker tumour suppressing effects than CD8+ iTSCM cells did." (PMID 28530241, 2017). "Moreover, a marked reduction in vascular endothelial growth factor (VEGF) expression, CD31+ blood vessels, CD4+ Foxp3+ Treg cells and the expression of MMP-2, MMP-9, MMP-13 and C-X-C motif chemokine receptor 4 (CXCR4) in the tumour stroma were observed in the Smad3−/− tumour microenvironment." (PMID 28262747, 2017). "In addition, intranasal delivery of CCL2 increases CD4+ T cell recruitment to the premetastatic niche of the lung, and this correlates with enhanced seeding and growth of tumor cells, while CCL2 shows a potential antitumor activity in tumor-entrained neutrophil-mediated tumor killing in vitro." (PMID 28589151, 2017).
tumor (continued). "Interestingly, the antitumor activity was observed to be dependent on the expression of EGFRvIII on some, but not all tumor cells, and the activity could be significantly inhibited in the absence of CD4+ and CD8+ T-cells." (PMID 28752098, 2017). "There is growing evidence that CD4+ CD5+ Treg cells may play an important role in suppressing the development of antitumor immunity in cancer patients and that the number of Treg cells is increased in tumor sites and/or the peripheral blood of patients with advanced tumors." (PMID 28409322, 2017). "We demonstrate in the tumor microenvironment that Listeria-based immunotherapy when combined with agonist anti-GITR Ab enhances both the CD8+ T cells as well as the number of non-Treg CD4+ T cells resulting in enhanced therapeutic effector cell/suppressor cell ratios." (PMID 28807056, 2017). "Accordingly, we hypothesized that combination of anti-GITR antibody (Ab) that enhances the number of effector CD4+ and CD8 T+ cells with immunotherapies that inhibit suppressive cells such as Tregs or myeloid-derived suppressor cells (MDSCs) will synergize to lead to a potent anti-tumor effect." (PMID 28807056, 2017). "In addition, it is of interest to explore whether normal reference ranges of CD4+CD25+FOXP3+ Treg could be established according to different age groups, which may make it possible to evaluate immune-activity against a tumour through regular monitoring of Treg populations." (PMID 28253320, 2017). "In addition, the preponderance of CD4, CD8, and CD57-positive lymphocytes being accessing to the tumor cells in the group immunized with alum-CpG-HH2-NY vaccine may also make certain contributions to tumor regression." (PMID 28515346, 2017). "Consequently, when CTLA-4 inhibitor was applied, CD4+T-cell proliferative capacity was enhanced, and the Treg/CD4+ T ratio was lowered although Treg numbers were not affected, which restored T-cell functional defects and produced stronger anti-tumor response in vitro." (PMID 27756892, 2017). "Thus deviation of CD4+ T cells away from a type 1 response could not account for tumor escape in our model." (PMID 27121060, 2016). "Interestingly, when we plotted the scores of CD4+ and CD8+ T cell infiltration in the tumor stroma against absolute total T cell numbers in the blood, patients without or with HGAOT fell into two separate, non-overlapping groups that could be completely delineated from each other." (PMID 27589568, 2016). "In summary, this study indicates that DLBCL patients with high PD‐1 expression on CD4+ T cells might damage T‐cell function, thereby leading to poor prognosis, while PD‐1 expression on peripheral blood CD4+ T cells does not reflect PD‐1 expression on cells in the tumor microenvironment." (PMID 27709793, 2016). "Moreover, immunofluorescence analysis in tumor tissue treated with combined vaccine were extensively infiltrated with higher numbers of CD4+T, CD8+T immune cells compared with the control, immune cell infiltration was observed not only around, but also inside the remaining tumor tissues." (PMID 29263903, 2016). "Indeed, our results support the hypothesis that the anti-tumor effect is more dependent upon differences in cytokine secretion between CD4+ and CD8+ cells rather than relative differences in tumor-infiltrating lymphocyte density." (PMID 27190629, 2016). "Overall the pooled Axl CRISPR tumours had the slowest growth and were the most sensitive to radiation, suggesting a greater immune response than the single Axl Cr #1 clone, which could be explained by greater CD45+ cells, mDCs, CD8+ cells, CD4+ cells and relatively fewer Tregs." (PMID 28008921, 2016). "An animal study showed that tumor-induced B10 could convert resting CD4+ non-Treg into Treg21." (PMID 27354007, 2016).
tumor (continued). "Furthermore, we recently found that the frequency of CD4+ T cells expressing Foxp3 was significantly decreased in the tumor but not in the spleen after HSCT and that the decrease in Tregs was dependent on interleukin‐6 (IL‐6) produced by dendritic cells in the tumor." (PMID 26589884, 2016). "Moreover, we observed statistically significant correlations between PD-1 and TIGIT expression in CD4+ T cells in AEM (r = 0.4769, p = 0.0159) and tumor tissues (r = 0.5121, p = 0.0089), and in CD8+ T cells in PBMC (r = 0.3888, p = 0.0210) and tumor tissues (r = 0.4793, p = 0.0153)." (PMID 27577071, 2016). "However, there was no change in the number of tumor-derived CD4+IL17A+ (Th17) cells." (PMID 27075020, 2016). "Indeed, CD4+ T-cells can also eliminate tumor cells in the absence of CD8+ T-cells." (PMID 25690042, 2015). "Whether functionally mature Tregs are recruited into the tumor microenvironment via cancer cell secreted chemokines or whether FoxP3 negative CD4+ T-cells are functionally converted into FoxP3+ Tregs by the cytokine milieu present within the tumor microenvironment is still controversial." (PMID 26690220, 2015). "Interestingly, only when these NPs were targeted to the tumor draining lymph node, the CD4+ T-cell distribution within the tumor repolarized towards a TH1 phenotype and an increased frequency of therapeutic antigen-specific CD8+ T cells within the tumor was observed." (PMID 26583156, 2015). "Interestingly, although tumor infiltrating SKAP55 KO or ADAP KO CD8+ T cells, as well as CD4+ effector/memory T cells, substantially reduced PD-1 expression during anti-tumor response, we did not observe any significant changes in CTLA-4 expression or infiltrating CD4+Foxp3+ Tregs in vivo." (PMID 25851535, 2015). "Thus, CD4+ T cells may also mediate upregulated expression of angiostatic chemokines such as CXCL9, CXCL10, and CXCL14 that are capable of inhibiting tumor growth or may downregulate expression of the chemokine receptor CXCR2 or its many ligands that promote angiogenesis." (PMID 26618181, 2015). "In addition, CD4+ T helper cells may function as effector cells either by the local production of cytokines (IFNγ and IL2) that curtail tumour growth or trigger the release of cytotoxic mediators towards MHC II tumour cells." (PMID 26081906, 2015). "However, antigen-specific TCR transgenic CD4+ T cells were used in these model systems, and may not reflect the physiological role of direct tumor recognition by CD4+ T cells." (PMID 26447332, 2015). "Interestingly, there are numerous examples of CD4 epitopes being presented in the absence of invariant chain expression, and that invariant chain-negative cancer cells have been used as a means to stimulate tumor-specific T cells." (PMID 26441969, 2015). "Interestingly, compared to CD8+ T cells from CD4 replete hosts, these bystander expanded cells displayed comparable (or enhanced) cytokine production, lytic ability, and in vivo anti-tumor effects suggesting no functional impairment or exhaustion and were enriched in an effector phenotype." (PMID 25119341, 2014). "Furthermore, it was found that there were increased proportions of tumor-infiltrating CD4+CD25+ T cells in patients with early stage NSCLC, and these CD4+CD25+ T cells were found to secrete immunosuppressive cytokine TGF-β, which may play a role in cancer progression." (PMID 24872958, 2014). "Moreover, hyperthermia at 50–55°C improved the CD4+/CD8+ ratio, further improved the cellular immune function and increased the level of immune factors, fully stimulating the organism’s antineoplastic immune response to inhibit the primary tumor and ectopic metastases." (PMID 24527084, 2014). "However, we have not determined whether the HLA-A2.1-restricted epitopes we identified are naturally processed and presented in tumor cells, nor have we identified longer epitopes that could also trigger CD4 T cell responses." (PMID 24690990, 2014).
tumor (continued). "Alternatively, preformed MHC-II–TAA peptide complexes derived from CIITA-transfected tumor cells could be shed from the cells, captured by professional APC and used by these cells to reach the AAA necessary to trigger an efficient priming of tumor-specific CD4+ TH cells." (PMID 24600588, 2014). "However, when tumor-activated γδ T cells were added, the proliferation of CD4+CD25− T cells was significantly increased (n = 3, P < 0.01), suggesting that tumor-activated γδ T cells, but not peripheral-derived γδ T cells, abrogate the immunosuppressive effect induced by CD4+CD25+ Treg cells." (PMID 24741609, 2014). "However, studies using several tumor models have shown that CD4+ T cells can efficiently eliminate major histocompatibility complex (MHC) class II expressing tumor cells as well as tumors lacking MHC class II molecules, demonstrating a direct role of CD4+ T cells in tumor rejection." (PMID 22890822, 2013). "The importance of CD4+ T cells in the therapeutic efficacy of SA-4-1BBL/SVN vaccine was also demonstrated as 88% mice succumbed to tumor growth after depletion of CD4+ T cells one day before inoculation with 3LL tumor cells as compared with 20% mice in the non-depleted control group." (PMID 24066030, 2013). "Moreover, MDSCs have been shown to skew the differentiation of CD4+ T cells into TREG, to induce an M2 phenotype in macrophages and to impair DC function, suggesting the existence of multiple overlapping regulatory mechanisms that dampen anti-tumor effector responses." (PMID 23616948, 2013). "After exposed to LF-MF, the proportion of Treg cells in normal mice (17.5% of the CD4+ population) had not increase compared with sham normal mice, while the proportion of Treg cells in tumor-bearing mice was declined to 22.2%, which was significantly less than that in sham MF tumor mice." (PMID 24314291, 2013). "Although it is increasingly clear that proinflammatory CD4+ effector T cells are critical determinants of effective antitumor immune responses, the utilization of CD4+ T cell-based immunotherapy in combination with chemotherapy to control tumor progression and recurrence has not been fully explored." (PMID 22400040, 2012). "Because iNKT cells in mice are either double negative (DN) or CD4+, but not CD8+, and are present in both CD4−/− and CD8−/− mice, these data raised the possibility that iNKT cells might play a role in potentiating tumor growth." (PMID 22880059, 2012). "However, mainly CD4+ T cells, which could constitute both T helper as well as immunosuppressive regulatory T cells, but not CD8+ T cells, expressed activation markers upon in vitro stimulation when obtained from tumor-bearing mice." (PMID 22674057, 2012). "Since we did not observe any major effect of SH2D2A on the in vitro responses of naïve TCR-transgenic CD4+ T cells, while there clearly was a difference in tumor protection, we examined whether presence of SH2D2A affected the in vitro response of TCR-transgenic CD4+ T from tumor-experienced mice." (PMID 23144743, 2012). "Secretion of immunoregulatory Th2 cytokines and IL-10 are generally associated with the CD4+ subset of human and nonhuman primate NKT lymphocytes, whereas DN NKT tend to have more effector properties in terms of Th1 cytokine secretion, cytotoxicity and greater anti-tumor efficacy." (PMID 23028326, 2012). "Finally, a recent study suggested that Cy may promote the differentiation of non-Treg CD4+ T cells into pro-inflammatory T helper 17 cells that enhance anti-tumor immunity." (PMID 22359647, 2012).